ANGPTL2 (angiopoietin like 2)
Diseases named in the same sentence as ANGPTL2 in open-access papers (continued):
Sharing a sentence is not in itself a finding about the gene and the disease.
peripheral arterial disease (2 papers, 2020 to 2025). A disorder of the arteries supplying the upper and lower extremity and the visceral organs. "In addition, clinical studies have reported that the ANGPTL2 level is a risk factor for lower extremity artery disease and lower extremity amputation in a large cohort of T2DM patients, while peripheral arterial diseases and amputation were the ultimate consequences of DFUs." (PMID 33256685, 2020).
skin cancer (2 papers, 2020 to 2023). "Interestingly, we previously showed that ANGPTL2 enhances TGF‐β signaling in lung and skin cancers and in renal tubular epithelial cells." (PMID 37452654, 2023).
Ureteral obstruction (2 papers, 2024 to 2026). Obstruction of the flow of urine through the ureter. "ANGPTL2 was essential for the progression of kidney fibrosis in mouse unilateral ureteral obstruction‐induced AKI by increasing TGF‐β expression." (PMID 39628378, 2024).
age-related macular degeneration (1 paper, 2016). Age-related loss of vision in the central portion of the retina (macula), secondary to retinal degeneration. "Angptl2 might therefore represent a multistep regulator of CNV pathogenesis and serve as a new therapeutic target for age-related macular degeneration." (PMID 26839315, 2016).
aneurysm (1 paper, 2021). Bulging or ballooning in an area of an artery secondary to arterial wall weakening. "Angptl2-deficient mice showed reduced AAA progression compared with wild-type mice; in particular, Angptl2-deficient mice exhibited smaller aneurysms, less vascular structural destruction, and lower MMP expression levels." (PMID 34194399, 2021).
artery thrombosis (1 paper, 2025). "Angptl2 deficiency accelerated mesenteric artery thrombosis induced by FeCl3 in Angptl2–/– compared to WT animals, promoted platelet granule secretion and aggregation induced by thrombin and collogen while purified ANGPTL2 protein supplementation reversed collagen-induced platelet aggregation." (PMID 38880861, 2025).
bladder tumor (1 paper, 2022). "The expression levels of a portion of feature genes, such as ANGPTL2, CAV1, FNBP1, FXD6, MAP1A, and ZCCHC24 were significantly decreased in bladder tumor cell lines." (PMID 35719407, 2022).
carotid atherosclerosis (1 paper, 2015). A thickening and loss of elasticity of the walls of carotid arteries that occur with formation of atherosclerotic plaques. "Third, due to the cross-sectional design of our present study, we could not assess the temporal relationship between the serum ANGPTL2 level and increased carotid atherosclerosis." (PMID 25889082, 2015).
Cerebral ischemia (1 paper, 2016). Restriction of arterial blood supply to the brain associated with insufficient oxygenation to support the metabolic requirements of the tissue. "Comparison of brain damage after acute brain ischemia between Angptl2 KO and WT mice suggests that ANGPTL2 modulates pro-inflammatory phenotypes and severity of brain damage after acute brain ischemia." (PMID 27861531, 2016). "Therefore, further investigations are needed to evaluate the effect of ANGPTL2 on brain ischemia in both acute and chronic states." (PMID 27861531, 2016). "To evaluate whether ANGPTL2 expression changes in conditions of acute brain ischemia, we evaluated Angptl2 mRNA levels in the affected cerebral hemisphere of forebrain compared to the contralateral hemisphere in a mouse transient middle cerebral artery occlusion (MCAO) model." (PMID 27861531, 2016). "Therefore, we next compared contributions of ANGPTL2 from brain resident cells (choroid plexus epithelial cells, ependymal cells, or activated microglia) and bone marrow-derived cells (infiltrating macrophages) in acute brain ischemia, using bone marrow chimeric model." (PMID 27861531, 2016).
colorectal tumors (1 paper, 2026). "Tumor development and ANGPTL2 expression in periodontal tissues, colorectal tumors, and serum were assessed by histology, immunostaining, and enzyme-linked immunosorbent assay." (PMID 41899283, 2026).
demyelinating disorders (1 paper, 2023). "Our study demonstrated an unexpected cross-talk between the environmental protein (ANGPTL2) and its surface receptor (MAG) in the regulation of oligodendrocyte differentiation, which may benefit the treatment of many demyelination disorders, including multiple sclerosis." (PMID 36855057, 2023).
demyelination (1 paper, 2023). "To further evaluate the role of ANGPTL2 in pathological states, we used a cuprizone-induced murine demyelination model and examined the dynamic changes in myelination in the corpus callosum." (PMID 36855057, 2023). "ANGPTL2-MAG-mediated signaling promoted the differentiation of oligodendrocytes in vitro and in vivo and enhanced remyelination in a cuprizone-induced demyelination murine model." (PMID 36855057, 2023).
esophageal cancer (1 paper, 2020). A primary or metastatic malignant neoplasm involving the esophagus. "Nevertheless, recent studies have shown ANGPTL2 as a potential serum biomarker for colorectal, gastric and esophageal cancer." (PMID 32082485, 2020).
fibrosis (1 paper, 2019). the formation of excess fibrous connective tissue in an organ or tissue in a reparative or reactive process. "We observed that Angptl2 in the 3 different fibrosis groups was always higher in the untreated group than the treated group." (PMID 31385666, 2019).
gout (1 paper, 2020). A condition characterized by painful swelling of the joints, which is caused by deposition of urate crystals. "If common genetic variation did not contribute to the epigenetic associations of PGGT1B, INSIG1, ANGPTL2, JNK1, and CNTN5 with gout, it would be interesting to clarify mechanisms underlying the differential methylation of these CpG sites in gout." (PMID 32630231, 2020). "Interestingly, some studies explored the relationships between molecules, INSIG1 and ANGPTL2, and gout." (PMID 32630231, 2020). "In gout patients, seven aberrant DNA methylation sites that were mapped to seven genes (PGGT1B, INSIG1, ANGPTL2, JNK1, UBAP1, RAPTOR, and CNTN5) and survived genetic and meQTL analyses or causal inference tests were discovered." (PMID 32630231, 2020). "In conclusion, this study provided evidence of aberrant methylation changes of PGGT1B, INSIG1, ANGPTL2, JNK1, UBAP1, RAPTOR, and CNTN5 in gout." (PMID 32630231, 2020). "Given the roles of PGGT1B, INSIG1, ANGPTL2, JNK1, UBAP1, RAPTOR, and CNTN5 in regulating IL-1β or gouty inflammation and differential methylation of these genes in gout, the next important topic is the consequence of manipulating the respective signaling pathways." (PMID 32630231, 2020). "Six (PGGT1B, INSIG1, ANGPTL2, JNK1, UBAP1, and RAPTOR) were novel genes in the field of gout." (PMID 32630231, 2020). "Moreover, measuring transcription factors identified in this study and chromatin immunoprecipitation (ChIP) for these transcription factors would provide more clues about the mechanistic link between PGGT1B, INSIG1, ANGPTL2, JNK1, UBAP1, RAPTOR, and CNTN5 methylation and gout." (PMID 32630231, 2020). "Taken together, these results suggested that relationships between PGGT1B, INSIG1, ANGPTL2, JNK1, UBAP1, RAPTOR, and CNTN5 methylation and gout were not confounded by genetic mediators." (PMID 32630231, 2020).
intestinal tumors (1 paper, 2017). "The relationship between ANGPTL2 expression and intestinal tumors warrants further investigation." (PMID 28043948, 2017).
ischemia (1 paper, 2016). A hypoperfusion of the BLOOD through an organ or tissue caused by a PATHOLOGIC CONSTRICTION or obstruction of its BLOOD VESSELS, or an absence of BLOOD CIRCULATION. "To investigate mechanisms underlying differences in brain damage after acute ischemia in Angptl2 KO and WT mice, we assessed inflammatory changes between genotypes." (PMID 27861531, 2016).
ischemic cardiomyopathy (1 paper, 2015). Ischemic cardiomyopathy is a cardiomyopathy in which a weakness in the muscle of the heart due to inadequate oxygen delivery to the myocardium with coronary artery disease being the most common cause. "Surprisingly, the HF patients with ischemic cardiomyopathy did not have significantly higher ANGPTL2 levels than those without ischemic cardiomyopathy (4.20 ng/mL (3.15–5.65 ng/mL) vs. 3.91 ng/mL (3.00–4.98 ng/mL], P = 0.13)." (PMID 26397985, 2015).
keloid (1 paper, 2025). An irregularly shaped, elevated mark on the skin caused by deposits of excessive amounts of collagen during wound healing. "Bioinformatic analysis of Angptl2 gene expression in published datasets of keloid and SSc patients and fibrotic diseases of other human organs, such as the lung, kidney, and liver, revealed that Angptl2 is upregulated in diseased skin compared with healthy skin controls." (PMID 40540411, 2025).
Left ventricular dilatation (1 paper, 2016). Enlargement of the chamber of the left heart ventricle. "Moreover, we were surprised to find that left ventricular dilatation in cases of DCM harbouring some ANGPTL2-associated cardiac dysfunction was milder than that seen in DCM cases lacking an association with ANGPTL2." (PMID 27677409, 2016).
leiomyoma (1 paper, 2014). A well-circumscribed benign smooth muscle neoplasm characterized by the presence of spindle cells with cigar-shaped nuclei, interlacing fascicles, and a whorled pattern. "Compared to leiomyomas, only a few pro-angiogenic factors such as TYMP, ANGPTL2 and PTGS1 were increased in PTSMT." (PMID 24398114, 2014).
lung adenocarcinoma (1 paper, 2023). A carcinoma that arises from the lung and is characterized by the presence of malignant glandular epithelial cells. "Furthermore, higher levels of ANGPTL2 expression in patients with lung adenocarcinoma were associated with lower survival." (PMID 36917086, 2023). "Records from the Gene Expression Omnibus (GEO) database (GDS4402/1431848_at) showed higher ANGPTL2 levels in lymph node metastatic tumor cells than in primary lung tumor cells from animal lung adenocarcinoma tissue." (PMID 36917086, 2023).
lymph node metastasis (1 paper, 2023). "Analysis of data from TCGA genomics program, the GEPIA web server and the Oncomine database revealed that higher levels of ANGPTL2 expression were correlated with progressive disease and lymph node metastasis." (PMID 36917086, 2023).
melanoma (1 paper, 2023). A malignant, usually aggressive tumor composed of atypical, neoplastic melanocytes. "In this study, melanoma patients in the ANGPTL2‐low group showed shorter overall survival after treatment with PD‐1 inhibitors than patients in the ANGPTL2‐high group." (PMID 37452654, 2023). "In fact, we found that ANGPTL2 mRNA levels were positively correlated with those of HLA‐A, HLA‐B, and HLA‐C in melanoma patients, suggesting that in this cancer context ANGPTL2 signaling does not regulate MHC‐I expression." (PMID 37452654, 2023). "ANGPTL2 is implicated in silencing MHC‐I expression in some types of cancer, but ANGPTL2 signaling may not repress MHC‐I expression in melanoma." (PMID 37452654, 2023).
Myocardial fibrosis (1 paper, 2022). "Angiopoietin-like 2 (ANGPTL2), which is also found in EAT, also positively correlated with the local concentrations of MMP2 and MMP9, as well as atrial collagen level, implicating its mediation of myocardial fibrosis." (PMID 34890279, 2022).
nonalcoholic fatty liver disease (1 paper, 2020). "Recent studies have shown that the Angptl2 pathway mediated hepatic inflammatory response plays an important role in the progression of nonalcoholic fatty liver disease." (PMID 32429849, 2020).
osteoporosis (1 paper, 2023). A condition of reduced bone mass, with decreased cortical thickness and a decrease in the number and size of the trabeculae of cancellous bone (but normal chemical composition), resulting in increased fracture incidence. "It was also worth noting that ANGPTL2 deletion was found to inhibit osteoclast formation and improve the symptoms of osteoporosis via suppressing the MAPK pathway." (PMID 36865085, 2023).
papillary thyroid cancer (1 paper, 2019). "Further evaluation needs to be done to analyze the possibility of taking ANGPTL2 as a prognostic marker and therapeutic target for papillary thyroid cancer." (PMID 31384179, 2019).
periodontal disease (1 paper, 2017). "Further studies are therefore necessary to determine how ANGPTL2 functions as a key mediator in periodontal disease and systemic diseases." (PMID 28934245, 2017). "To date, functional data on the pathophysiological roles of ANGPTL2 in periodontal disease are scarce." (PMID 28934245, 2017). "We hypothesized that ANGPTL2 might play an important role as a unique mediator in both systemic and periodontal disease." (PMID 28934245, 2017). "Interestingly, during periodontal disease progression, the pathway has an autocrine effect in which ANGPTL2 acts as an exacerbating factor." (PMID 28934245, 2017). "We tested the hypothesis that ANGPTL2 is a unique mediator in periodontal disease by conducting a series of in vivo and in vitro experiments." (PMID 28934245, 2017). "However, no studies have yet investigated a role for ANGPTL2 in the pathogenesis of inflammatory disease, including periodontal disease." (PMID 28934245, 2017).
proliferative diabetic retinopathy (1 paper, 2024). Advanced retinopathy due to diabetes mellitus characterized by the formation of new vessels in the retina. "The ROC indicated that VEGF-A and ANGPTL2 act as risk biomarkers for the prediction of proliferative diabetic retinopathy with an area under the curve of 0.86 (p-value<0.001) when compared with control (T2DM without DR) and found the optimal cut-off value with the best diagnostic performance." (PMID 39350883, 2024).
psoriasis (1 paper, 2023). An autoimmune condition characterized by red, well-delineated plaques with silvery scales that are usually on the extensor surfaces and scalp. "In addition to adipocytes, several cells involved in psoriasis and HS pathogenesis can secrete ANGPTL2, such as macrophages, keratinocytes, and endothelial cells." (PMID 37189824, 2023).
renal cell carcinoma (1 paper, 2023). "We previously demonstrated that angiopoietin‐like protein 2 (ANGPTL2) promotes tumor progression using a Xp11.2 translocation renal cell carcinoma (tRCC) mouse model." (PMID 37452654, 2023).
Renal insufficiency (1 paper, 2017). A reduction in the level of performance of the kidneys in areas of function comprising the concentration of urine, removal of wastes, the maintenance of electrolyte balance, homeostasis of blood pressure, and calcium metabolism. "The first link between ANGPTL2 and kidney disease has been described in patients with diabetic glomerulopathy in whom upregulation of ANGPTL2 expression in microvascular lesions was associated with a higher prevalence of renal insufficiency." (PMID 29138671, 2017).
Sepsis (1 paper, 2016). Sepsis is defined as life-threatening organ dysfunction caused by a dysregulated host response to infection. "In addition, we also recently reported down-regulation of ANGPTL2/Arap1 function in sepsis-induced hypotension due to reduced AT1A receptor recycling in vascular cells." (PMID 27677409, 2016).
thyroid tumor (1 paper, 2019). A benign or malignant neoplasm affecting the thyroid gland. "Similarly in TCGA’s data, with increasing of thyroid tumor severity stage, ANGPTL2 mRNA expression levels increased." (PMID 31384179, 2019).
tumor (58 papers, 2001 to 2026). "Postmortem analysis of HFD‐fed ANGPTL2‐deficient mice revealed reduced tumor development, which is consistent with our previous findings that ANGPTL2 signaling in tumor cells promotes tumor progression." (PMID 41508557, 2026). "Here, we demonstrate that Angptl2 deficiency in tumor cells enhances the activation of CD8+ T cells in kidney tissues and slows tumor progression in a tRCC mouse model." (PMID 37452654, 2023). "In conclusion, ANGPTL2 reduces tumor cell susceptibility to CD8+ T‐cell‐mediated anti‐tumor immune responses by promoting PRC2‐mediated repression of MHC‐I expression in tumor cells, thereby accelerating tumor progression." (PMID 37452654, 2023). "Here, we report that ANGPTL2 deficiency in renal tubular epithelial cells slows tumor progression in the tRCC mouse model and promotes activated CD8+ T‐cell infiltration of kidney tissues." (PMID 37452654, 2023). "We also found that Angptl2‐deficient tumor cells show enhanced interferon γ‐induced expression of MHC‐I and increased susceptibility to CD8+ T‐cell‐mediated anti‐tumor immune responses." (PMID 37452654, 2023). "Angptl2 fosters the polarization of tumor-associated macrophages (TAMs) through the p65 nuclear factor-kappa B (NF-κB) pathway and functional M2 phenotype." (PMID 34447409, 2021). "High expression of ANGPTL2 is associated with tumor malignancy, early recurrence, and poor prognosis in GC patients." (PMID 32352015, 2020). "However, molecular mechanisms underlying ANGPTL2 tumor‐promoting activity in the tRCC model remained unclear." (PMID 37452654, 2023). "Next, we asked whether Angptl2 deficiency in tumor cells promotes intracellular MHC‐I antigen processing." (PMID 37452654, 2023). "Moreover, we previously reported that cancer‐associated fibroblast‐derived ANGPTL2 enhances CD8+ T‐cell‐mediated anti‐tumor immune responses." (PMID 37452654, 2023). "Furthermore, CKO tRCC mice showed a significant increase in the CD8+ T‐cell population among infiltrating lymphocytes relative to tRCC mice, suggesting that Angptl2 deficiency in tumor cells enhances CD8+ T‐cell infiltration of kidney tissues." (PMID 37452654, 2023). "Our findings provide novel insight into mechanisms underlying tumor immune evasion and suggest that blocking ANGPTL2 signaling in tumor cells could be a potential strategy to promote tumor elimination by T‐cell‐mediated anti‐tumor immunity." (PMID 37452654, 2023). "In addition, ANGPTL2 is reportedly upregulated in tumor‐associated fibroblasts (TAFs) from anti‐VEGF‐resistant tumors, suggesting that fibroblast‐derived ANGPTL2 functions in tumor development." (PMID 28043948, 2017). "Consequently, we investigated whether ANGPTL2 affects endothelial cells in a manner that would cause loss of tight junctions and passage of tumor cells across the endothelial barrier." (PMID 32082485, 2020). "Further studies are needed to dissect these mechanisms and clarify the conditions under which ANGPTL2 acts as a tumor promoter versus a tumor suppressor." (PMID 41508557, 2026). "Several high-scoring proteins, including ITGB8, LGR5, FZD7, HLA-E, ANGPTL2, and BST2 emerged as candidates potentially affected by protonation-linked perturbations in acidic tumor microenvironments." (PMID 42036641, 2026). "Consistent with this, previous reports have shown ANGPTL2 to have important roles in tumor angiogenesis in various cancers." (PMID 40540411, 2025). "ANGPTL2 is a multifaceted secreted glycoprotein acting on endothelial cells promoting angiogenesis but has also been shown to have roles in inflammation and tumor expansion." (PMID 38822135, 2024). "We previously demonstrated that ANGPTL2 has a dual function in tumor progression in both the tRCC mouse model and a murine syngeneic model." (PMID 37452654, 2023). "We also demonstrated that Angptl2‐deficient tRCC cells show enhanced intracellular MHC‐I antigen processing, leading to accelerated CD8+ T‐cell activation and tumor cell eradication." (PMID 37452654, 2023).